CCKBR (cholecystokinin B receptor)
Diseases named in the same sentence as CCKBR in open-access papers (continued):
Sharing a sentence is not in itself a finding about the gene and the disease.
type 2 diabetes (3 papers, 2019 to 2025). "Whether other endocrine cells, such as delta cells, which express the CCKBR gastrin receptor, are also increased in islets of individuals with type 2 diabetes remains unknown." (PMID 31430329, 2019). "This study aims to determine the role of intestinal Gastrin/CCKBR on glucose absorption in the development of type 2 diabetes (T2D)." (PMID 39950948, 2025). "The gastrin/CCKBR axis inhibits the expression of SGLT1 and GLUT2 through the PI3K/AKT/eIF4B signaling pathway, thereby preventing type 2 diabetes." (PMID 40733369, 2025).
Barrett esophagus (2 papers, 2017 to 2021). Esophageal lesion lined with columnar metaplastic epithelium which is flat or villiform. "Cholecystokinin 2 receptor (CCK2R, also known as CCKBR), which regulates gastric stem cells in the cardia or antrum regions of the stomach, is also upregulated in Barrett's esophagus and in esophageal adenocarcinoma." (PMID 33532680, 2021).
bipolar disorder (2 papers, 2016 to 2025). A disorder of the brain that causes unusual shifts in mood, energy, activity levels and the ability to carry out day-to-day tasks. "The “cases” are all from a cohort of patients with bipolar disorder, which poses the question as to whether the significant CCKBR polymorphisms might be associated with bipolar disorder and not with suicide attempts." (PMID 27721799, 2016).
gastritis (2 papers, 2017 to 2018). Inflammation of the stomach. "Consequently, gastrin-CCKBR level is a vital standard for measuring the severity of gastritis." (PMID 30382864, 2018). "Moreover, ZJW may exert its therapeutic effects through inhibiting the expression of IL-12β and CCKBR, cutting down the opportunity of further deterioration of gastritis." (PMID 30382864, 2018).
prostate carcinoma (2 papers, 2016 to 2021). A carcinoma that arises from epithelial cells of the prostate gland. "Considering that prostate cancer cells also express CCKBR and respond to CCK stimulation, the effects of high-fat diet on prostate tumor progression reported previously may well be a consequence of CCK elevation." (PMID 26700819, 2016). "Surprisingly, prostate cancer cell lines were found to actively expressing the CCK receptor CCKBR." (PMID 26700819, 2016).
adenoma (1 paper, 2022). A neoplasm arising from the epithelium. "Moreover, CCKBR are widely expressed in colorectal polyps, the activation of CCKBR occurs in the early stage of adenoma progression to cancer and promotes tumor progression." (PMID 36176299, 2022).
asthma (1 paper, 2023). "Thus, the use of devazepide or other highly selective CCKAR antagonists would be a priority for asthma drug repurposing to limit the undesirable effects brought by the possibility of blocking the other CCK receptor (CCKBR)." (PMID 36599824, 2023).
cocaine addiction (1 paper, 2023). "The CCKBR signal in the brain has anti-reward effects, and CCKBR receptor antagonists may have utility in treating cocaine addiction." (PMID 37962470, 2023).
leiomyoma (1 paper, 2020). A well-circumscribed benign smooth muscle neoplasm characterized by the presence of spindle cells with cigar-shaped nuclei, interlacing fascicles, and a whorled pattern. "The expression of CCKBR was also identified in gastroenteropancreatic tumors, leiomyomas and leiomyosarcomas indicating wide application prospects of the radiolabeled minigastrin analogues for diagnosis and therapy of the CCKBR-positive cancers." (PMID 33198403, 2020).
Pain (1 paper, 2023). An unpleasant sensory and emotional experience associated with actual or potential tissue damage, or described in terms of such damage. "It is well known that cholecystokinin B receptor and its neuropeptide ligand are upregulated in chronic neuropathic pain and stress models." (PMID 37446213, 2023).
renal fibrosis (1 paper, 2025). A final common manifestation of a wide variety of chronic kidney diseases characterized by glomerulosclerosis and tubulointerstitial fibrosis. "Mechanistically, gastrin, an agonist of cholecystokinin receptor B (CCKBR), enhances PPAR‐α transcription by promoting CCKBR nuclear translocation and promotes efferocytosis of apoptotic renal tubular cells by macrophages, thereby ameliorating renal fibrosis and lowering blood pressure." (PMID 39748782, 2025).
Zollinger-Ellison syndrome (1 paper, 2018). Zollinger-Ellison syndrome (ZES) is characterized by severe peptic disease (ulcers/esophageal disease) caused by hypergastrinemia secondary to a gastrinoma resulting in increased gastric acid secretion. "In a few smaller biopsies from normal gastric mucosa and gastric mucosa from a patient with Zollinger-Ellison syndrome, weak expression of CCKBR mRNA was in addition to ECL cells noted in gastric epithelial cells below the isthmus of the glands." (PMID 28980157, 2018). "In two separate biopsies, one from a patient with normal gastric mucosa and one from a patient with Zollinger-Ellison syndrome, CCKBR were observed in most cells below the isthmus area of the glands." (PMID 28980157, 2018).
tumor (100 papers, 1989 to 2026). "For instance, the higher expression of CCKBR was associated with upregulated sensitivity of tumor cells to nelarabine, idarubicin, pipobroman, decitabine, thiotepa, fluphenazine, triethylenemelamine, raltitrexed, cytarabine and hydroxyurea." (PMID 36176299, 2022). "A431/CCKBR tumor–bearing nude mice were analyzed after administration of a daily 50 mg/kg dose of SAHA for 10 d, alone or in combination with a single 30-kBq dose of 225Ac-PP-F11N." (PMID 36732057, 2023). "The pioneer clinical studies with CCKBR-specific radiolabeled minigastrin analog [177Lu]Lu-PP-F11N demonstrated tumor-specific accumulation with low adverse reactions in MTC patients." (PMID 36612012, 2022). "Apart from a low kidney and bone marrow radiation dose, the latter study reported [177Lu]Lu-PP-F11N uptake by stomach tissue, which expresses CCKBR, and suggested stomach as a dose-limiting organ with a tumor-to-stomach dose ratio of 3.34." (PMID 34959437, 2021). "Another difference between PANC-1 and Panc02.13 cells is that the former expresses high levels of the cholecystokinin-B receptor (CCK-BR) that is responsible to tumor growth when activated and the Panc02.13 cells lack CCK-BR and only have CCK-AR." (PMID 34944824, 2021). "In our study, high tumor uptake of [225Ac]Ac-PP-F11N and [177Lu]Lu-PP-F11N was observed in the A431/CCKBR xenograft nude mice." (PMID 33198403, 2020). "Studies done on patients with CAG and NETs treated with the CCKBR antagonist netazepide, have shown promising results in terms of decrease in tumor size and in some patients complete remission." (PMID 28980157, 2018). "In conclusion, we found that all eight NENs expressed CCKBR and neuroendocrine markers in a majority of tumor cells." (PMID 28980157, 2018). "As a hormone has direct effects only on cells having the receptor, patients selected for such a trial would need to express CCKBR on their tumor cells." (PMID 28980157, 2018). "Expression of CCKBR was also observed in a number of cases with adenocarcinoma of the diffuse and intestinal types, but in a lower number of tumor cells when compared with NENs." (PMID 28980157, 2018). "The cell surface G protein coupled receptor CCKBR (Gene 1D#887) is overexpressed in many types of cancers and plays a role in tumor cell proliferation." (PMID 27754762, 2017). "The lack of blood–brain barrier penetration is additional evidence that tumor targeting with a CCKBR AP offers significant advantages over gastrin targeting." (PMID 27754762, 2017). "Natural CCKBR ligands gastrin and CCK, as well as CCKBR antagonists, have been attached to nanocarriers, radionuclides, and imaging agents to improve their uptake by tumor cells." (PMID 27754762, 2017). "A plethora of studies have shown the significant role that upregulation of CCKBR and its endogenous ligands play in the regulation of tumor growth and maintenance." (PMID 29262666, 2017). "Blockade of the CCKBR with antagonists, or reduction of gastrinor CCKBR in cancer cells, has been shown to inhibit tumor formation and metastasis, and to promote apoptosis." (PMID 25346875, 2013). "Moreover, gastrin has been demonstrated to facilitate tumor growth via paracrine and autocrine mechanisms mediated by the cholecystokinin-B receptor (CCK-BR), which has been found to be expressed in approximately 50% of GC patients." (PMID 40599798, 2025). "In conclusion, as revealed by the present study, enhanced tumor-specific uptake of [177Lu]Lu-PP-F11N due to increased CCKBR level in response to mTORC1 inhibition by RAD001, has the potential to substantially improve efficacy of PRRT and nuclear imaging of radiolabeled minigastrin analogues." (PMID 33042258, 2020). "In the RAD001-treated A431/CCKBR-tumor mouse model, we observed enhanced CCKBR-specific uptake of the radiolabeled minigastrin in tumors, but not in the healthy organs such as the gastrointestinal tract which expresses endogenous CCKBR." (PMID 33042258, 2020).
tumor (continued). "Here, we demonstrate a clinically feasible way for augmented tumor-specific uptake of [177Lu]Lu-PP-F11N by the pharmacological interference with mTORC1 activity, which led to increased CCKBR protein levels in cancer cells, and consequently higher uptake of radiolabeled minigastrin." (PMID 33042258, 2020). "Examination of CCKBR may help to tailor treatment, and if a tumor expresses CCKBR, a CCKBR antagonist may be applied." (PMID 28980157, 2018). "Interestingly, in case 7, all the stages from ECL cell hyperplasia, NET and NEC were observed, and further examination with IHC and ISH clearly demonstrated positivity for both CgA and CCKBR in all the various components of the tumor." (PMID 28980157, 2018). "Codelivery of theranostic agents to both tumor and stellate cells, both of which express CCKBR, could further enhance treatment options for cancer patients." (PMID 27754762, 2017). "However, evidence is also accumulating for paracrine growth effects of gastrin, where for example blockade of CCKBR signaling has been shown to reduce tumor fibrosis and inflammation." (PMID 25346875, 2013). "Here we review the literature on the effects of gastrin:CCKBR signaling on various processes in stroma, and develop the idea that pancreatic stellate cells (PSCs) and tumor infiltrating macrophages (TIMs) may be important players in mediating such effects." (PMID 25346875, 2013). "In addition, it is possible that gastrin peptides on the NP surface could activate the CCKBR, stimulating the proliferation of tumor cells." (PMID 27754762, 2017). "Compared with CCKBR, the function of CCKAR in tumorigenesis and tumor progression is much less studied." (PMID 36733361, 2022). "Significant anti-tumor effects were observed based on these groupings, and the high expression group of CCKBR and KCNJ11 showed better anti-tumor effects." (PMID 34675134, 2021). "The ectopic and over-expression of GPCRs such as CCKBR, GRPR, B1R, and other receptors, drives tumor growth." (PMID 29262666, 2017). "There are many validated miRNA-148a’s target genes contributing to the tumor metastatic behavior, including MMP7, ROCK1, SMAD2, Met and cholecystokinin B receptor (CCK-BR)." (PMID 28199399, 2017). "MiR-148a-3p, down-regulated in GC, was shown to influence tumor cell growth, migration, adhesion, invasion and angiogenesis in GC by targeting CDKN1B (p27), NR1I2 (PAR2) and CCKBR genes." (PMID 26172537, 2015). "The over-expression of gastrin and gastrin receptors(CCKBR) and cyclooxygenase-2(COX-2) may stimulate tumor growth, angiogenesis, and reduce apoptosis." (PMID 39434880, 2024). "Hyperactivation of mTORC1 was reported in many human cancers, including CCKBR-positive primary MTC and lymph node metastases, whereas mTORC1 inhibition is known to reduce tumor angiogenesis and induce apoptosis as well as to enhance cancer sensitivity towards therapy-induced DNA damage." (PMID 34959437, 2021). "The post-therapy SPECT/CT images of [111In]In-PP-F11N in the mice with no visible tumor from 45 and 60 kBq [225Ac]Ac-PP-F11N groups indicate no detectable CCKBR positive tumor left." (PMID 33198403, 2020). "The biodistribution studies of [225Ac]Ac-PP-F11N revealed CCKBR-specific uptake in tumors, whereas the therapeutic studies demonstrated dose-dependent inhibition of tumor growth and extended mean survival time, without apparent toxicity." (PMID 33198403, 2020). "Our data demonstrate desirable biodistribution and therapeutic efficacy in A431/CCKBR tumor-bearing nude mice without toxic effects and thus, provides preclinical evidence for the development of safe and efficacious CCKBR-targeted α particle therapy (TAT)." (PMID 33198403, 2020). "The post-therapy SPECT-CT images with [111In]In-PP-F11N confirmed no CCKBR-positive tumor left in the mice with complete remission." (PMID 33198403, 2020). "Surprisingly though, one of the NECs (case 8) with high CCKBR mRNA expression did not express any CCKBR protein in the tumor." (PMID 28980157, 2018).
tumor (continued). "Interestingly, in ECL cell hyperplasia and NETs there was co-expression of CCKBR and CgA or HDC in almost all normal ECL- cells and ECL-derived tumor cells." (PMID 28980157, 2018). "The results also established that CCKBR/ERK/P65 signaling function is generally tumor suppressive in ER+ BC, indicating therapies should focus on restoring, not inhibiting, CCKBR/ERK/P65 pathway activity." (PMID 30115027, 2018). "This tumor was surrounded by mostly CCKBR negative carcinoma cells, but the GIST itself expressed copious amounts of CCKBR mRNA." (PMID 28980157, 2018).
cancer (56 papers, 2011 to 2026). A tumor composed of atypical neoplastic, often pleomorphic cells that invade other tissues. "Nevertheless, mTORC1 inhibition by everolimus has the potential to substantially improve the response of CCKBR-positive cancers to RLT." (PMID 36612012, 2022). "The present study demonstrates the superior therapeutic efficacy of the combinatory treatment with RAD001 and [177Lu]Lu-PP-F11N over monotherapy without severe adverse effects in a preclinical mouse model of CCKBR-positive cancer." (PMID 34959437, 2021). "After binding to the CCKBR, receptor-bound radiolabeled PP-F11N undergoes internalization and the cytotoxic radiation is delivered into the cancer cells." (PMID 33198403, 2020). "The overexpression of cholecystokinin B receptor (CCKBR) in human cancers led to the development of radiolabeled minigastrin analogues for targeted radionuclide therapy, which aims to deliver cytotoxic radiation specifically to cancer cells." (PMID 33198403, 2020). "Overexpression of CCKBR described in several types of cancers led to the development of CCKBR-targeted therapeutic agents." (PMID 30115027, 2018). "Receptor autoradiographic studies revealed that CCKBR is expressed in high percentages in lung and pancreatic cancers, medullary thyroid carcinomas, some ovarian cancers, astrocytomas, gastrointestinal tumor, and colorectal cancer." (PMID 29262666, 2017). "In GC, it was noted that both miR-148a and miR-152 were down-regulated in cancer tissue and cell lines, involving the cholecystokinin B receptor (CCKBR) protein." (PMID 26627200, 2015). "Among the possible candidates, we further analyzed DNMT1, CCKBR, WNT10B, NOG and ROBO1, which are five genes whose functions have been associated with carcinogenesis or cancer development." (PMID 21205300, 2011). "Recently, it was reported that CCKBR expressed in almost all kinds of cancers, and none of the cancer samples showed the higher CCKBR expression than that in the paired non-cancer samples." (PMID 30115027, 2018). "More importantly, CCKBR inhibition was found to suppress the promoting effect of adipocytes on spheroid formation of the cancer cells, supporting that adipocytes stimulate prostate CSC self-renewal by facilitating the activation of the CCK/CCKBR autocrine loop." (PMID 26700819, 2016). "By assessing whether the cancer cells express CCKBR or not, one can determine which patients may experience benefits from treatment with a CCKBR antagonist." (PMID 28980157, 2018).
adenocarcinoma (4 papers, 2013 to 2020). A common cancer characterized by the presence of malignant glandular cells. "The staining of CCKBR was mainly cytoplasmatic, and the staining intensity mainly moderate for NENs, and weak to moderate in the adenocarcinomas." (PMID 28980157, 2018). "When examined for CCKBR mRNA 12 of 29 (41%) adenocarcinomas expressed this marker, where five of ten (50%) intestinal types, five of 15 (33%) diffuse types and two of four (50%) mixed/indeterminate types expressed this marker." (PMID 28980157, 2018). "Of the 29 adenocarcinomas examined, 12 tumors expressed CCKBR mRNA, and 11 of these tumors co-expressed CgA mRNA." (PMID 28980157, 2018). "As NENs are known to express NE markers and CCKBR, these are considered a gold standard and described separately from the adenocarcinomas." (PMID 28980157, 2018). "Of the 20 tumors expressing CCKBR mRNA, eight were NENs and 12 were adenocarcinoma." (PMID 28980157, 2018). "CCKBR was expressed in 26 of 29 (90%) adenocarcinomas, where positive cases were observed in nine of ten (90%) intestinal type adenocarcinomas, 14 of 15 (93%) diffuse type adenocarcinoma, and three of four (75%) mixed/indeterminate type adenocarcinomas." (PMID 28980157, 2018). "Co-expression of CCKBR mRNA and CgA mRNA and CCKBR mRNA and HDC mRNA was frequently observed, which makes sense as the NENs and even some cases of adenocarcinomas of the diffuse type are thought to originate from ECL cells." (PMID 28980157, 2018). "Our hypothesis was that CCKBR is expressed in ECL cell hyperplasias and NENs, and we wanted to see if the same was the case for adenocarcinomas." (PMID 28980157, 2018). "Therefore, the expression of CCKBR (in 90% of adenocarcinomas by IHC, and 41% by ISH) was not unexpected." (PMID 28980157, 2018).
infection (3 papers, 2013 to 2021). The state of being infected such as from the introduction of a foreign agent such as serum, vaccine, antigenic substance or organism. "The expression levels of the cholecystokinin B receptor (CCKBR) and histidine decarboxylase (HDC), which are implicated in histamine production by enterochromaffin like cells, were not impacted by the infection." (PMID 24330735, 2013).
CCKBR also shares sentences with these, for which no sentence is quoted: astrocytoma (10 papers); neuroendocrine tumors (9); stromal ovarian cancer (9); gastrointestinal stromal tumor (6); depression (5); epidermoid carcinoma (5); glioma (5); hepatocellular carcinoma (5); Peptic ulcer (4); gastric tumor (3); gastro-intestinal tumours (3); morphine dependence (3); thyroid cancer (3); colorectal tumor (2); diabetic neuropathy (2); gastric ulcer (2); gastroenteropancreatic neuroendocrine tumors (2); hyperglycaemia (2); Hypocalcemia (2); leukemia (2); metastatic disease (2); non-small cell lung carcinoma (2); Allergy (1); Alzheimer disease (1); anxiety disorder (1); blood pressure (1); carcinoid tumour (1); cognitive deficits (1); colon adenocarcinoma (1); colorectal polyps (1).
A further 48 diseases each share a sentence with CCKBR in 1 paper.